CD55 (CD55 molecule (Cromer blood group))
Diseases named in the same sentence as CD55 in open-access papers (continued):
Sharing a sentence is not in itself a finding about the gene and the disease.
cancer (continued). "Complement regulatory proteins, CD55, CD59, MCP, CD46, FH, and FH-like proteins are often upregulated in cancers with variations among cancer types and tumor specimens of the same cancer type." (PMID 40309765, 2025). "Both CD55 and FGF2 are known to be involved in tissue remodeling and protection, the regulation of fibroblast activity, and cancer development and immune evasion." (PMID 40725231, 2025). "These marker genes play diverse roles in cancer, such as promoting growth and proliferation (MYC, HIF1A, ATM), inhibiting apoptosis (MCL1, BIRC3, BCL2) and facilitating invasion (CXCR4, CD55)." (PMID 38982317, 2024). "As the CD59/CD55‐deficient phenotype is measured in the human erythrocyte PIG‐A assay, it might be hypothesized that cisplatin‐induced GPI‐deficient PIG‐A mutant erythrocytes in cancer patients are under pressure for elimination by the complement system, as occurs in PNH patients." (PMID 38214136, 2024). "We performed a Pearson correlation analysis of ADGRE5, CD55 and IL32 in the pan-cancer TCGA database." (PMID 38343549, 2024). "Low expression of terminal elements (C8A, C8B, and C9) was detected in all cancer types, whereas complement regulators (C1inh, FH, FI CD46, CD55, and CD59) are highly expressed in most cancers." (PMID 38003705, 2023). "Based on these findings, we developed an asymmetric bispecific antibody (SBU-CD55 × CD20) that simultaneously targets both CD55 and CD20 to effectively eliminate rituximab-resistant cancer cells." (PMID 37880350, 2023). "We found cancer stem cell gene, CD24 (logFC = 0.9), and therapy resistant genes, CD46 (logFC = 0.3) and CD55 (logFC = 0.4) expressed in ES1, ES2, and ES3 combined, compared to ES0, and cancer stem cell marker, CD59 to be the highest in ES1 (logFC = 0.4)." (PMID 38328306, 2023). "Membrane-bound CRPs such as CD55 (DAF) and CD59 (MSK21) are known to inhibit complement activity and are often upregulated in cancer, with some prognostic capacity in HER2+ BC patients." (PMID 35167491, 2022). "Inhibition of complement activation via the overexpression of complement-regulatory proteins (CRPs), most notably CD46, CD55 and CD59, is an efficient mechanism of disguise of cancer cells from a host immune system." (PMID 35563599, 2022). "The expression levels of several cancer stem cell (CSC) markers, CD55, CD133, OCT4, and ALDH1 were also increased at both transcription and protein level when cells were cultured with additional cancer cell-derived exosomes." (PMID 34692546, 2021). "Cancer cells are known to express, and sometimes overexpress, the membrane complement inhibitor proteins CD46, CD55, and CD59." (PMID 33126570, 2020). "Herein, CD97iso knockdown decreased CD55 expression, suggesting that CD97-mediated CD55 knockdown disrupts the membrane attack complex and exposes carcinoma cells to complement attack." (PMID 26233326, 2016). "Cancer cells, in particular, possess membrane complement regulatory proteins (mCRPs such as CD46, CD55 and CD59) on their surfaces to ultimately thwart MAC pore formation and only allow for about 50%–60% cancer cell kill rates in vitro." (PMID 24276022, 2013). "Meanwhile, CD55 and CD46 on malignant cells restrict deposited C4b and C3b, and CD59 inhibits complement membrane attack complex formation, therein protecting cancer cells from membrane damage." (PMID 17623109, 2007). "Since there is an ever-going debate as to whether the complement system is pro- or anti-cancer, we aimed in the current study to investigate the expression pattern of two important complement regulatory proteins; CD46 and CD55 in ALL and AML cancer patients." (PMID 41526546, 2026). "CD55 was also significantly down regulated (P < 0.05) with approximately 3.8 fold in AML and ALL patients suggesting the possibility that cancer may evade complement attack mechanism and may even manipulate it to its benefit." (PMID 41526546, 2026).
cancer (continued). "The results of our analysis suggested that CD55 expression in patients was up-regulated with increasing disease duration (or in TCPTC), potentially activating complement and coagulation cascade pathway, thus promoting cancer cell dedifferentiation." (PMID 40535127, 2025). "CD55 can stimulate CD97 to trigger downstream signaling and promote cancer metastasis." (PMID 40596619, 2025). "Here, we demonstrated that statin could also upregulate CD55 expression on hMSCs and that erlotinib, an FDA-approved EGFR inhibitor for the treatment of cancer, was able to increase CD55 expression on hMSCs." (PMID 37357314, 2023). "Regarding infectivity, cancer cells may also overexpress different surface receptors, such as CD46, ICAM-1, CD55, CD155 or integrins, allowing OVs to infect cancer cells." (PMID 35493490, 2022). "However, previous studies have reported a significant downregulation of membrane-bound complement regulators (CD46, CD55, and CD59) in SCLC compared to other cancers, including NSCLC." (PMID 34996345, 2022). "Removal of GPI-anchored proteins, which include the complement-regulatory proteins CD59 and CD55 but not CD46, with PI-PLC treatment resulted in enhanced susceptibility of cancer cells to complement lysis." (PMID 35227072, 2022). "It has been hypothesized that cancer cells escape from complement system by activating complement inhibitors, such as CD59, CD46, and CD55." (PMID 32922663, 2020). "Moreover, the membrane-bound complement regulatory proteins (mCRPs), including MCP (CD46), DAF (CD55), and CD59, have been found overexpression in many cancer cells." (PMID 33614473, 2020). "Thus, by suppressing C3 deposition on the cancer cells, CD46 and CD55 can lower, on one hand, the extent of MAC generation and CDC, and on the other hand, reduce immune protection through complement-dependent cellular cytotoxicity." (PMID 31024572, 2019). "In addition, the expression of membrane-bound complement regulatory proteins (mCRPs), including CD46, CD55 and CD59, is upregulated in many types of cancer cells, which can dwarf antitumor therapeutic efficacy." (PMID 31787848, 2019). "Like all normal cells, cancer cells are protected from autologous complement attack by several specific cell-surface complement inhibitors: CD55 (decay accelerating factor, DAF), CD46 (membrane cofactor protein, MCP), CD59, and CD35 (complement receptor type 1, CR1)." (PMID 31024572, 2019). "Although CD97 and CD55 are expressed by cells to protect them from the complement immune system, the presence of a small population that strongly expresses CD97 and CD55 predicts poor prognosis in a number of cancers." (PMID 25624904, 2015). "The upregulation of CD55 and the possible role of the CD55-CD97 interaction in invasion and metastasis promotion have led to the development of compounds which target CD55, as an immunotherapeutic approach for cancer treatment." (PMID 25624904, 2015). "Should the complement cascade override the effects of CD55 (and CD46, another mCRP) and manage to activate the terminal complement components on cancer cell membranes, functional CD59 molecules bind to human C8 and C9, during the attempt to properly assemble the membrane attack complex." (PMID 17623109, 2007). "It has been reported that CD46, CD55 and CD59 could protect cancer cells from MAC-mediated CDC." (PMID 31787848, 2019). "Additionally, several different complement-regulatory proteins (CRPs) function to inhibit complement activation, and certain membrane-bound CRPs such as CD46, CD55, and CD59 were reported to be aberrantly expressed in various cancers, which likely confers resistance to CDC." (PMID 29354121, 2017). "In addition, the expression of CD55 (a checkpoint inhibitor in the CDC cascade) was significantly increased in a rituximab-resistant cell line generated in-house, suggesting that CD55 overexpression might be a mechanism by which cancer cells acquire rituximab resistance." (PMID 37880350, 2023).
cancer (continued). "Whether CD55 and/or CD59 play a role in protecting cancer cells from mAb-mediated CDC in vivo is not completely clear." (PMID 33126570, 2020). "Interestingly, the expression of CD46, CD55, and CD59 was suppressed in U2-OS cells compared with human endothelial cells or other cancer cells which did not activate the complement system." (PMID 29615744, 2018).
infection (64 papers, 2009 to 2025). The state of being infected such as from the introduction of a foreign agent such as serum, vaccine, antigenic substance or organism. "CD55/GPI supplemented cells treated with PLC were resistant to Echo7 infection, consistent with GPI anchor cleavage by PLC." (PMID 41252368, 2025). "We treated control, CD55 KO, or CD55 complemented cells with PLC and then tested their susceptibility to Echo7 infection." (PMID 41252368, 2025). "We have shown that PIG genes are required for efficient Echo7 infection; the simplest explanation is that PIG genes support Echo7 infection through CD55 synthesis." (PMID 41252368, 2025). "The efficacy of AAV-CD55 in inducing CD55 expression was verified through the infection of 293T cells." (PMID 40862775, 2025). "ANDV infection showed upregulation of cell type-specific viral entry genes (Calu-3: CD55 and ITGB3; hPSC-astrocytes: MERTK and VEGFA)." (PMID 40857262, 2025). "PIV5 infection upregulates cell surface CD55 to produce progeny virions containing increased levels of CD55 which leads to enhanced resistance to C’-mediated neutralization." (PMID 39791880, 2025). "Taken together, these results showed that the GPI anchor transfer genes are necessary for efficient Echo7 infection through mechanisms that are distinct from CD55 expression and viral entry." (PMID 41252368, 2025). "P14 cells in acute LCMV infection had a smaller frequency of these cells, which transitioned through a CD61+CD55+ cell population before almost entirely consisting of CD61−CD55+ TSCM cells by day 12 (d12) of infection." (PMID 40062995, 2025). "Certain echovirus serotypes (6, 7, 11, 12, 20, and 21) and enterovirus 70 exploit the complement regulator CD55 as a receptor for attachment and infection." (PMID 41031883, 2025). "While P14 cells in chronic LCMV showed some transition to CD61−CD55+ TSCM cells, the CD61+CD55− TPEX cell population was maintained at d14 of infection." (PMID 40062995, 2025). "The broad impact of CD55 on the infection of cells by a range of enterovirus strains has been previously documented, including CVA21, CVB3, and CVB5, as well as E6, E7, E11, E12, and E30." (PMID 39940693, 2025). "PIGS- or PIGK-KO cells supplemented with CD55/TM were restored for CD55 expression, however, these cells still showed impaired infection and resistance to Echo7-induced cell death." (PMID 41252368, 2025). "Overall, transcriptomic analysis, cytokine measurements, and antibody ELISA results indicated that CD55 deletion affected innate and IgM responses following infection." (PMID 36036625, 2022). "CD55 KO mice had a significantly lower spirochete burden at 2 dpi, suggesting a role for CD55 during the early phase of infection." (PMID 36036625, 2022). "In our studies, we did not see differences in Rae-1 (distantly related to MHC class I proteins) expression in CD55 KO mice following infection with B. crocidurae." (PMID 36036625, 2022). "For example, human protein CD55 (complement decay-accelerating factor) was related to infection by coxsackievirus." (PMID 30815000, 2019). "WT StcE, but not its catalytic mutant, was able to reduce surface levels of CD55, confirming that the protease activity of StcE is responsible for cleaving CD55 from the host cell surface during infection." (PMID 30190327, 2018). "Clusters 1 and 2 chiefly comprised proteins that were transcriptionally upregulated, including CD55, which is known to be upregulated during infection." (PMID 30122656, 2018). "The complement decay–accelerating factor cluster of differentiation 55 (CD55) exhibited the greatest reduction in cell-surface levels during infection." (PMID 30190327, 2018). "Cumulatively these results suggest that a secreted bacterial protease, specific to EHEC, is likely responsible for cleavage of CD55 from the cell surface during infection." (PMID 30190327, 2018).
infection (continued). "Of the wild-type animals, 75% had positive blood cultures, whereas only 37.5% of the Cd55-/- blood cultures were positive 24 h after infection." (PMID 21984892, 2011). "While wild-type mice all died at day 3 after infection (median survival time = 64.5 h), Cd55-/- lived up till day 5 after infection (median survival time = 111.3 h)." (PMID 21984892, 2011). "PLC treatment could ablate Echo7 infection of control cells, while CD55 KO cells treated with PLC were similarly resistant to infection as non-treated cells." (PMID 41252368, 2025). "We next employed this CD55/TM molecule to evaluate the role of PIGS or PIGK during Echo7 infection." (PMID 41252368, 2025). "This may be attributed to the role of CD55 in cell infection, as it only facilitates virion attachment to the cell surface." (PMID 39940693, 2025). "CD55 was then overexpressed in the CT26 cell line using lentiviral infection." (PMID 40596619, 2025). "The goal was to investigate whether inferred CD55–CXADR protein variations yielded a wide enough range of infection outcomes in the model that one or both receptors could be nominated as a susceptibility factor." (PMID 39333715, 2024). "CD55 and FcRn are the key receptors involved in Echo11 infection." (PMID 39767680, 2024). "In general terms, CD55 could represent a potential therapeutic target to regulate the infection rate of such viruses in the future." (PMID 39337843, 2024). "We hypothesised that CD55 would be increased during infection with more virulent strains of H. pylori, and with more marked gastric mucosal pathology." (PMID 35851954, 2022). "To test this hypothesis, and further validate our proteomics data, we focused on the protein exhibiting the greatest reduction from the host cell surface during infection, CD55." (PMID 30190327, 2018). "Western blot analysis confirmed that neither infection with EHEC EDL933 ΔstcE nor exposure to EHEC EDL933 ΔstcE culture supernatants caused CD55 cleavage, as no CD55 was detected in HeLa cell culture supernatants." (PMID 30190327, 2018). "However, the roles of CD55 and FcRn in the infection process differ among various echoviruses." (PMID 39767680, 2024). "Consequently the complement pathway functioning changes by increased expression of genes C2, C3, C4, CD55, and factor H, which may be needed as an early defence mechanism against dysbiosis/infection or a dysfunctional barrier." (PMID 37789352, 2023). "The negative regulators of the complement system, CD55 and CD59a, were also investigated due to their importance in maintaining homeostasis and keeping the complement system in its proper physiological state in response to altered physiological conditions (i.e. infection and/or neurodegeneration)." (PMID 29859100, 2018). "For example, in constructing a mass-action model of cardiomyocyte infection by coxsackievirus B3 (CVB3), RNA-seq was used to estimate abundances of the serial CVB3 receptors, CD55 and CXADR." (PMID 39333715, 2024). "Parainfluenza virus type 5 (PIV5) recruits cellular C’ inhibitors CD55, CD46 and CD59 during budding, and PIV5 infection upregulates the synthesis of CD55 to produce virions with enhanced resistance to neutralization by C’." (PMID 35062233, 2021). "During acute infection (7 dpi), PRRSV significantly represses the expression of complement regulatory components (CD55 and C4BPB) in lung tissue." (PMID 32731586, 2020). "We used flow cytometry analysis to quantify the cell-surface levels of CD55, CD46, and CD59 during infection." (PMID 30190327, 2018). "Consistent with earlier work, regulators of complement activation, CD46, CD55 and CD59, were slightly enhanced after VV and VV:ΔHA infection (unpublished results)." (PMID 21901096, 2011). "GPI-anchored CD55 (DAF) and CD66e (Carcinoembryonic antigen; CEA) are recruited by diffusely adhering Escherichia coli (Afa/Dr DAEC) strains during infection of CaCo-2 cells." (PMID 19832981, 2009).
infection (continued). "The observed effect of CD55 on cell infection with CVA7 or E25 strains has not been previously reported." (PMID 39940693, 2025). "CD55 (complement accelerating factor) and FGF2 (fibroblast growth factor 2) were two genes whose increased expression correlated with viral RNA levels both before and after infection." (PMID 40725231, 2025). "As highlighted earlier, TKO/CD55 and TKO/CD55/CD46/TM pigs raised under the same conditions showed no signs of infection, suggesting that general housing environments are generally safe." (PMID 39902050, 2024). "In response to ONNV MOI 1, SC reduced CD55 and CD59 gene expression by about two-fold (2.89 × 10−3 ± 1.41 × 10−3, p < 0.05) and three-fold (1.19 × 10−2 ± 3.31 × 10−3, p < 0.05), respectively, at 24 h post infection." (PMID 36611893, 2022). "The observation that the CD55 mRNA levels declined at later times post-infection whereas the protein levels did not suggests that differences in turnover rate contribute to the greater expression of CD55 compared to CD46." (PMID 33652918, 2021). "Since, we wanted to preserve the virus entry to be able to induce immune responses by unleashing the critical viral proteins, but not lytic infection leading to tissue injury, we chose not to target and disrupt the virus attachment to CD55." (PMID 34127684, 2021). "The differential levels of CD55 and CD46 in VSV-infected cells prompted us to investigate the pattern of incorporation of these proteins into the virus envelope as a function of time post infection." (PMID 33652918, 2021). "Next, we infected HeLa cells with A. nosocomialis M2 expressing CpaA and CpaAE520A at three different multiplicities of infection (MOI) (10, 100, and 1,000) and used flow cytometry analysis to quantify the levels of cell surface exposed CD55 and CD46 postinfection." (PMID 33024038, 2020). "Indeed, CD55 and CD59 expression were generally higher in subjects who recuperated from an infection with E. Coli O104:H4 than in HC." (PMID 24086391, 2013). "Likewise, coxsackievirus serotypes B1, B3, B5, and A21 bind CD55 for cellular attachment, although this interaction alone does not mediate productive infection." (PMID 41031883, 2025). "In contrast, CD55/TM supplemented cells still could support Echo7 infection regardless of PLC treatment." (PMID 41252368, 2025). "Additionally, gastric CD55 was enhanced in areas of IM which generally occur at a later stage of infection, suggesting that CD55 is not a main adhesin for H. pylori." (PMID 35851954, 2022). "Also, the local concentration of the pro-inflammatory cytokines TNFα and IL-1β and the chemokines KC and MIP-2 was not different between wild-type and Cd55-/- mice at 24 h and 48 h after infection (data not shown)." (PMID 21984892, 2011). "To confirm that PIG genes support Echo7 infection not solely through CD55 production, we need to evaluate the function of PIG genes without affecting functional CD55 expression." (PMID 41252368, 2025). "Our data do not support a role for CD55 and CD59 in HUS development during EAHEC O104:H4 infection and point to a different mechanism within the complement system for HUS development in EAHEC patients." (PMID 24086391, 2013). "These include IL10, Cd55 (complement decay-accelerating factor) and Cxcr4 (CXC chemokine receptor 4), which all have plausible roles in the response to infection but there were no published SNP in exons of any of these and no SNP in conserved intergenic regions." (PMID 21085469, 2010).